SMAD2 (SMAD family member 2)
Diseases named in the same sentence as SMAD2 in open-access papers (continued):
Sharing a sentence is not in itself a finding about the gene and the disease.
glioma (continued). "In an in vitro cell line-based model increased protein levels of pSMAD2/3, total SMAD2/3 and SMAD4 were observed in murine BV2 microglia cultured in glioma conditioned medium (GCM), indicative of the activated TGFβ signaling pathway in microglia associated with glioma environment." (PMID 29861845, 2018). "Thus, this evidences suggests that HOXA13 knockdown may cause G0/G1 arrest by inhibiting SMAD2/SMAD3 pathway and this process could be regulated by HOTTIP in glioma." (PMID 26356815, 2015). "RelB knockdown cells displayed diminished RNA expression of the mesenchymal genes N-Cadherin/CDH2, SMAD2 and TGFβ3, as well as lower levels of YKL-40/CHI3L1, a biomarker of aggressive and recurrent gliomas that is very strongly associated with the mesenchymal glioma subtype." (PMID 23451236, 2013). "Another example of stemness and migration under the effect of TGF-β was shown in work: in glioma cells, TAM-derived TGF-β1 upregulated EMT markers (vimentin and N-cadherin) via the Smad2/3 pathway." (PMID 38794298, 2024). "In glioma, M2 macrophages can promote the stemness and migration abilities of glioma cells by secreting TGF-β1 via the SMAD2/3 signaling pathway." (PMID 37779195, 2023). "In glioma cells, miR-205-5p regulates TGF-β1 by targeting SMAD2, thereby influencing the immune response of TGF-β1 in tumors." (PMID 35712349, 2022). "Similar to human glioma, mRNA levels of TGFB1 receptor (BRI; 17-fold; **P < .01) and the downstream transcription factor SMAD2 (4-fold; *P < .05) were increased in high-grade astrocytoma compared to normal brain." (PMID 34131649, 2021). "Another recent study reported that EMP3 directly interacts with TGFBR2 in glioma cells, which subsequently activates the TGF‐β/Smad2/3 pathway and enhances tumor progression in vitro and in vivo." (PMID 34268874, 2021). "We observed an activating role for sTβRIII for Smad2 phosphorylation both in TGF-β1- and TGF-β2-mediated signaling in glioma cells." (PMID 33772427, 2021). "In the present study, we showed that diosmetin inhibits TGF-β signaling in glioma cells by suppressing the expression of TGF-β and elevating the levels of the active forms of Smad proteins (i.e., p-Smad2 and p-Smad3)." (PMID 31906574, 2020). "In fact, miR‐195 expression is known to affect the TGF‐β signaling pathway by targeting SMAD2 and SMAD7 genes in glioma–U87 cell line." (PMID 31581360, 2019). "As SMAD2/3 forms a complex with SMAD4 to regulate TGFβ responsive genes, the effect of glioma microenvironment on SMAD4 expression in microglia was determined by western blot and immunocytochemistry." (PMID 29861845, 2018). "Western blot analysis for a phosphorylated Smad2, an active component of TGFβ signaling pathway, was performed on total extracts from microglia polarized with GCM from glioma cells." (PMID 29963047, 2018). "Meanwhile, we found that the phosphorylated levels of TGFBR1, Smad2 and Smad3 and the nuclear levels of Smad2/Smad3 were markedly increased in the SMC4-overexpressing glioma cells but decreased in the SMC4-silenced cells." (PMID 28287612, 2017). "To explore the role of TGF-β/Smad2/3 and NF-κB in the regulation of cell proliferation, we treated SF295, A172 and LN18 glioma cells with TGF-β receptor inhibitor SB431542 and IKKβ inhibitor SC-514." (PMID 27527869, 2017). "In glioma, SOX4 expression is directly induced by TGF-β activated SMAD2/3, resulting in the maintenance of sternness and tumorigenicity." (PMID 23301048, 2013). "In glioma cell lines, SMAD3 level and SMAD2 nuclear translocation was lower in 9 out of 10 cell lines." (PMID 22943793, 2012).
glioma (continued). "SMAD2, SNAIL, and ZEB1 are transcription factors involved in TGF-β signaling and epithelial-to-mesenchymal transition, which enhance the invasive phenotype of GBM cells, promoting glioma cell invasion and migration." (PMID 40286187, 2025). "In glioma stem cells, FHL3 inhibits the Smad2/3-SOX4-SOX2 axis." (PMID 35686099, 2022). "However, it was confirmed that SOX4 can also promote tumor progression by interacting with the transcription factors Smad2/3 as well as dephosphorylating PPM1A and FHL3, which decreases the self-renewal capacity of glioma stem cells." (PMID 35686099, 2022). "Moreover, inhibition of USP15 leads to the decrease in TGF-β type I receptor levels and phosphorylated SMAD2 concentrations in these cells thus inhibiting TGF-β/SMAD2 signaling, and glioma progression." (PMID 31744193, 2019). "Therefore, the present study investigated how downregulation in the expression levels of Smad2 and Smad3 affected glioma cell proliferation, and whether GBM cell proliferation was controlled differentially by Smad2 and Smad3." (PMID 25891822, 2015). "Using Western blot analysis with specific anti-pSmad2 antibodies, we demonstrated that both the FAP-upregulating U87 glioma cells and FAP-non-upregulating AZVU001A glioma stem-like cells were capable of rapidly phosphorylating the Smad2 protein when exposed to TGFbeta-1." (PMID 33494271, 2021).
ovarian carcinoma (40 papers, 2009 to 2026). A malignant neoplasm originating from the surface ovarian epithelium. "Here, in this study, we have demonstrated that in DDB2-deficient ovarian cancer cells, phosphorylated Smad2 was hardly increased by TGF-β treatment." (PMID 26130719, 2015). "INHBA+ cancer-associated fibroblasts drive SMAD2-dependent PD-L1 expression and promote regulatory T-cell differentiation in advanced ovarian cancer, nominating INHBA protein/RNA and CAF-PD-L1 as tissue surrogates of TGF-β superfamily–linked immune suppression." (PMID 41181126, 2025). "SMAD2/3 have been linked to the promotion of EMT in ovarian cancer involving the TGFB pathway." (PMID 37370765, 2023). "We then transiently overexpressed Smad2 and Smad3 in ovarian cancer cells, CAOV3 and SKOV3, respectively, and found that only the overexpression of Smad2 increased the mRNA levels of USP9X." (PMID 40246814, 2025). "For instance, KLF8 is activated by transforming growth factor-β1 (TGF-β1) via SMAD2 and contributes to ovarian cancer progression." (PMID 38256218, 2024). "Our study demonstrated that FBXO28 facilitates malignant behavior of ovarian cancer cells via activation of TGF-b1 /SMAD2/3 pathway." (PMID 38267923, 2024). "KRT7 regulates EMT in ovarian cancer via the TGF-ß/Smad2/3 pathway, and regulates cell-matrix adhesion through integrin-ß1-focal adhesion kinase signaling." (PMID 37954148, 2023). "We detected a higher expression of phosphorylated P65 and Smad2 in tumor specimens from ovarian cancer patients with thrombocytosis." (PMID 35626102, 2022). "Keratin 7, a molecule of the keratin family, has been characterized to drive EMT of ovarian cancer cells through the TGF-β/SMAD2/3 pathway." (PMID 36248424, 2022). "It was observed in a recent publication that KRT7 overexpression in ovarian cancer cell lines was associated with increased proliferation, migration and EMT marker expression through the regulation of the TGF-β/Smad2/3." (PMID 34070214, 2021). "We evaluated the usefulness of YAP, TEAD4, SMAD2, SMAD3, H2A.X, ALD1A1, CD71, TKT and TKTL1 as diagnostic or prognostic markers in patients with ovarian cancer." (PMID 34205023, 2021). "TGFβ1 is significantly up-regulated in exosomes from CAFs in ovarian cancers with omental metastasis; TGFβ1 promotes EMT in ovarian cancer through activation of SMAD2/3 signaling." (PMID 32957712, 2020). "Activation of SMAD2/3 signaling is a known downstream effect of TGF-β signaling, and we observed enrichment of the SMAD2/3 signaling pathway in CD105-high ovarian cancer cell lines and tumors." (PMID 31684072, 2019). "In the present study, we confirmed that the blockade of UCHL5 activity by the DUB inhibitor bAP15 inhibited expression of phospho-Smad2/Smad3 in a concentration-dependent manner and induced apoptosis in ovarian cancer cells." (PMID 31666925, 2019). "We also examined the phosphorylation levels of SMAD2/3 in ovarian cancer cells after exogenic TGFβ1 stimulation." (PMID 29221185, 2017). "Confocal imaging of tissue sections showed intense staining of p-SMAD2 in human ovarian cancer (ii) compared to normal (i) tissues, supporting the activation of TGF-β signalling pathway." (PMID 26298390, 2015). "PD169316 has been shown to inhibit Smad2 phosphorylation in human ovarian cancer cells and ES cells (; CY unpublished)." (PMID 19440553, 2009). "Our findings define the TGF-β/SMAD2 axis as a central driver of NK cell dysfunction in ovarian cancer and demonstrate that bi-specific CAR-NK platforms offer a robust therapeutic solution to bypass TME-induced suppression and restore antibody-mediated tumor suppression." (PMID 41744817, 2026).
ovarian carcinoma (continued). "Within the stromal compartment, immunomodulatory cancer-associated fibroblast subsets, including INHBA+ CAFs that enforce SMAD2-dependent PD-L1 expression and regulatory T-cell differentiation, exemplify TGF-β–linked suppressive circuits in advanced ovarian cancer." (PMID 41181126, 2025). "Therefore, FBXO28 exerts its oncogenic function partly by targeting the TGF-b1/p-Smad2/3 axis in ovarian cancer." (PMID 38267923, 2024). "Furthermore, the nuclear expression of Smad2 decreased when the cells were treated with bAP15, as in our previous study of ovarian cancer cell lines." (PMID 37762005, 2023). "In this paper, we investigate whether Wnt5A is associated with the TGF-β1/Smad2/3 and Hippo-YAP1/TAZ-TEAD pathways, implicated in epithelial to mesenchymal transition (EMT) in epithelial ovarian cancer." (PMID 35053353, 2022). "Consistently, FAM46A levels were positively correlated with p-Smad2 expression (r = 0.63; P < 0.05) in 10 freshly collected clinical ovarian cancer samples, further suggesting that FAM46A expression was clinically correlated with activities of TGF-β/Smad pathways in ovarian cancer." (PMID 35465837, 2022). "There was no statistical significance in the expression of mRNA for SMAD3, and borderline statistical significance for SMAD2 between the groups of ovarian cancer patients and other subgroups of patients with simple cysts and healthy ovarian tissue (p = 0.709 and p = 0.053, respectively)." (PMID 34205023, 2021). "Furthermore, high level of p‐Smad2 staining in different ovarian tumour types is observed which stimulates the ovarian cancer progression." (PMID 34288373, 2021). "There was no statistical significance in the expression of mRNA for SMAD3, and there was borderline statistical significance for SMAD2 between the groups of ovarian cancer patients and other subgroups of patients with simple cysts and healthy ovarian tissue (p = 0.726 and p = 0.046, respectively)." (PMID 34205023, 2021). "In ovarian cancer, FoxO3a interacted with a SMAD2/SMAD3/SMAD4 complex in the nucleus, which could maintain activated SMAD proteins at high levels, and this interaction in turn promoted the cell-cycle arrest synergistically." (PMID 31640193, 2019). "In addition, PITX2-activated TGF-β signalling pathway was evidenced by p-SMAD2 induction as well as its nuclear localization by PITX2-CM in ovarian cancer cells." (PMID 26298390, 2015). "Moreover, we plan to determine whether FBXO28 can promote ovarian oncogenesis via regulation of TGF-b1 and SMAD2/3 signaling pathways in ovarian cancer." (PMID 38267923, 2024). "We knocked down AP3S1 in ovarian cancer cells and observed a decrease in the protein levels of TGF-β, phosphorylated SMAD2/3 (p-SMAD2/3), vimentin (VIM), and N-cadherin, whereas E-cadherin levels were increased." (PMID 38609993, 2024). "TGF-β/SMAD2/KLF8 axis regulates epithelial–mesenchymal transition (EMT) and contributes to ovarian cancer progression." (PMID 39057685, 2024). "Silencing Wnt5A by siRNAs significantly decreased Smad2/3 activation and YAP1 expression and nuclear shuttling in ovarian cancer (OvCa) cells." (PMID 35053353, 2022). "We evaluated the differences in the expression of the YAP, TEAD4, SMAD2, SMAD3, H2A.X, ALD1A1, CD71, TKT, and TKTL1 in ovarian cancers and benign cysts." (PMID 34205023, 2021). "Epithelial ovarian cancer tissues showed a decrease in TGF-β1 I receptor (p < 0.05) and a change in Smad2/3 protein levels." (PMID 26091707, 2016). "Given that NEDD4L plays an important role in constraining transforming growth factor β signaling by targeting activated Smad2/Smad3 for degradation, we investigated the role of DDB2 in the regulation of TGF-β signaling in ovarian cancer cells." (PMID 26130719, 2015).
ovarian carcinoma (continued). "Previous research showed that PD169316 was a specific inhibitor of p38 MAPK by inhibiting the phosphorylation and nuclear translocation of SMAD2 and SMAD3 induced by TGFβ, and it has been well studied in human ovarian cancer cells and in equine digital vein endothelial cells." (PMID 37686221, 2023). "In ovarian cancer cells, platelet-derived TGF-β increased the invasive potential of tumor cells and induced EMT by increasing the phosphorylation of SMAD Family Member 2 (Smad2)." (PMID 34322381, 2021). "Phospho- and total SMAD2 in EIF5A2 KO and control ovarian cancer cells was examined by WB." (PMID 33827661, 2021). "Smad2/Smad3 represent direct targets of TGF-β receptor kinase 1 and mediate transcriptional regulation through their intrinsic ability to bind to DNA; their phosphorylation plays a crucial role in the pathogenesis of ovarian cancer." (PMID 31666925, 2019). "The phosphorylation of STAT1α by TGF-β1 leads to its activation and the dissociation of STAT1α from TβRII/ALK5 receptor complex that releases the blockage and, in turn, increases the phosphorylation of Smad2, executing TGF-β signal transduction in ovarian cancer cells." (PMID 29751820, 2018). "Given that NEDD4L is the principle ubiquitin ligase targeting activated Smad2/3 to constrain the signaling capacity of the TGF-β pathway, it is likely that NEDD4L impacts the progression of ovarian cancer through compromising the responsiveness of cancer cells to TGF-β stimulation." (PMID 26130719, 2015). "Members of the FOXO subfamily were previously shown to cooperate with SMAD2/3–SMAD4 to induce CDKN1A (also called p21Cip1) in epithelial cells in response to TGF-β, and FOXO3 has previously been shown to cooperate with the SMADs to regulate cyclin induction in ovarian cancer." (PMID 35302162, 2022).
colon carcinoma (39 papers, 2011 to 2025). "Mutational analysis suggest that majority of mutations of MH1 and MH2 domains of Smad2 are missense mutations, however, in colon cancer Smad2 had two cases of homozygous deletion mutations." (PMID 35295334, 2022). "Since Smad2 and Smad3 are rarely mutated in colon cancer, Smad2 phosphorylation was used in this study to indicate active TGF-beta/Smad2/3 signaling." (PMID 23536895, 2013). "Indeed, human colon carcinoma cell lines of known Ras activating mutations show a correlation between the oncogenic Ras and a deficient nuclear accumulation of activated Smad2 and Smad3." (PMID 29534718, 2018). "Additional studies indicated that the activin A/ACVR2A axis promotes metastasis in colon cancer by selectively activating SMAD2." (PMID 40444773, 2025). "Overexpression of the cell adhesion molecule L1 induces higher expression of ezrin-dependent PLOD2 by reducing SMAD2/3 in colon cancer, which stimulates cell proliferation, tumorigenesis, and liver metastasis." (PMID 39068670, 2024). "Neuropilin-2 expression on colon cancer cell lines has been shown to enhance transforming growth factor-1 signaling, likely to result in Smad2/3 complex phosphorylation that persists." (PMID 35052853, 2022). "miR-190 restrains Smad2/4 as the key transcription factors of the TGF-β signaling pathway in colon cancer." (PMID 36820302, 2022). "The initial researches have revealed that Nodal was higher in human colon cancer tissues than that in adjacent noncancerous colon tissues, and Nodal was shown to accelerate self-renewal of human colon cancer stem cells via Smad2/3 signaling pathway." (PMID 34257534, 2021). "Further studies suggested that ADAM8 modulated EMT on colon cancer cells through TGF‐β/Smad2/3 signalling pathway." (PMID 32954649, 2020). "In a word, these results indicated that ADAM8 was involved in the regulation of EMT processes in colon cancer cells through activating TGF‐β/Smad2/3 signalling pathway." (PMID 32954649, 2020). "Our results suggest that the actions of TrkC are positioned upstream of Smad2 and Smad3 phosphorylation; therefore, we examined the possibility that TrkC directly interacts with TβRII in normal colon cells and colon cancer cells." (PMID 28455963, 2017). "Based on these results, we conclude that hsa-miR-140-5p directly regulates Smad2 expression in colon cancer cell lines." (PMID 25980495, 2015). "We highlight that Nodal is involved in self-renewal of colon cancer stem cell via an autocrine manner through the activation of Smad2/3 pathway." (PMID 24696849, 2014). "Overall, our results indicate that Nodal facilitates the self-renewal of human colon cancer stem cell via an autocrine Smad2/3 pathway." (PMID 24696849, 2014). "In contrast, two hub genes of colon cancer, SMAD2 and SMAD3, are from the TGFβ/SMAD signaling pathway whose role is more established for the development of colon cancer compared to the other two cancer types." (PMID 22691569, 2012). "The expression of neuropilin-2 on colon cancer cell lines was indeed shown to promote transforming-growth factor-β1 signaling, leading to a constitutive phosphorylation of the Smad2/3 complex." (PMID 21747928, 2011). "In particular, ADAM8 could promote colon cancer cell invasion by activating the TGF-β/Smad2/3 signaling pathway to induce EMT." (PMID 38025763, 2023). "The role of TGF-β/Smad2 in colon cancer has been reported in various studies." (PMID 35310912, 2022). "However, we failed to observe significant alterations in Smad7 expression and Smad2/3 phosphorylation upon overexpression or suppression of Nur77 in colon cancer cells, suggesting a distinct mode of Nur77 action in colon cancers." (PMID 33990575, 2021).